LEP (leptin)
Diseases named in the same sentence as LEP in open-access papers (continued):
Sharing a sentence is not in itself a finding about the gene and the disease.
lipodystrophy (continued). "Prolonged HU also induced significant lipodystrophy in mice as evidenced by significantly decreased body fat mass, decreased serum leptin levels, increased lean body mass, and increased MAT volume when compared to AMB controls." (PMID 34836964, 2021). "In 2002, leptin replacement was initially tested in nine female patients with lipodystrophy, and the therapy was shown to be effective in treating the disease." (PMID 33935782, 2021). "As the adipose tissue is the primary source of the hormone leptin, lipodystrophy is characterized by a striking reduction in circulating leptin levels." (PMID 34638939, 2021). "Using this approach in groups of patients that included various types of lipodystrophy, it has been shown that the treatment with recombinant leptin decreased hunger and increased satiety." (PMID 33411809, 2021). "Patients with lipodystrophy usually show low leptin levels; in our review, only 14 reported patients harboring PPARγ2 variants were evaluated for leptin levels, 4 of which had low leptin levels." (PMID 34764936, 2021). "Biological signs of adipose dysfunction include decreased serum adiponectin, and either barely detectable leptin levels in generalized lipodystrophies, or lower leptin levels than predicted by body mass index in partial lipodystrophies." (PMID 35046902, 2021). "Studies comparing different types of lipodystrophy found that both leptin and adiponectin levels are particularly low in the generalized forms, with even lower levels found in the congenital than in the acquired generalized variants." (PMID 33411809, 2021). "Since lipodystrophy is a medical condition characterized by degenerative adipose tissue, leptin production in patients is significantly reduced." (PMID 33935782, 2021). "Consistently, tall stature has been described in patients with lipodystrophy who exhibit low levels of leptin and high levels of insulin." (PMID 34002033, 2021). "The only drug that has been approved for treatment of lipodystrophy is metreleptin, a recombinant analogue of human leptin used as leptin replacement therapy to treat the metabolic complications of generalized lipodystrophy, but not that of FPLD." (PMID 34865644, 2021). "Recombinant human leptin (metreleptin) therapy can be used to minimize and prevent complications of lipodystrophy." (PMID 31434462, 2020). "Fatty liver develops in cases of defective leptin signaling as it happens in ob/ob mice, db/db mice and fa/fa Zucker rats and in cases of lipodystrophy, in which leptin levels are extremely low." (PMID 33316927, 2020). "Leptin has also been tested as a possible therapeutic strategy in patients with lipodystrophy, that present hypoleptinemia due to the reduced adipose tissue and NAFLD." (PMID 33316927, 2020). "Metreleptin, a recombinant analogue of human leptin, is the only specific therapy available for the management of human lipodystrophies that improve insulin sensitivity." (PMID 33233602, 2020). "Here the authors describe a patient with inflammatory bowel disease and lipodystrophy, providing evidence that leptin aggravates intestinal inflammation with proinflammatory effects on leukocytes that are reversible by TNFα blockade." (PMID 31822667, 2019). "Leptin replacement therapy (metreleptin) has been found to improve metabolic parameters in many patients with lipodystrophy." (PMID 29704234, 2019). "Metreleptin, the synthetic analog of the adipocyte-derived hormone leptin and current therapy of choice for patients with lipodystrophy, successfully improves metabolic function." (PMID 31656583, 2019). "While surprising, this observation is in keeping with the capacity of small amounts of leptin to reverse the metabolic complications of lipodystrophy and the substantially greater bone mass in FF relative to other lipodystrophic mice with some residual fat." (PMID 31233501, 2019).
lipodystrophy (continued). "A key feature of lipodystrophy is a drastic reduction in the levels of adipocyte-derived hormones including leptin, which is a major regulator of appetite, insulin sensitivity, and liver function." (PMID 31656583, 2019). "Strong basic science and clinical evidence have demonstrated that daily supplementation with leptin in rodent models of lipodystrophy and patients with lipodystrophy restores appetite, glycemia, and hepatic and renal function." (PMID 31656583, 2019). "Taken together, these results further support the direct vascular effects of leptin and indicate that metreleptin treatment should improve vascular function in lipodystrophy patients." (PMID 31656583, 2019). "Leptin, an adipokine secreted principally by adipocytes, is dramatically reduced in patients with lipodystrophy." (PMID 31222048, 2019). "Specific studies should be done to determine the capacity of leptin in restoring adipogenesis within the different forms of lipodystrophy." (PMID 31920961, 2019). "Leptin is a protein involved in weight regulation and energy homeostasis, and leptin levels are altered in obese individuals as well as in those with lipodystrophy." (PMID 30356397, 2018). "In fact, the leptin analog Metreleptin was approved by the U.S. Food and Drug Administration for the long-term treatment of lipodystrophy." (PMID 29467755, 2018). "Consistent with lipodystrophy, Otg1PB/PB mice had circulating leptin below detectable level (<0.2 ng/ml) at P11." (PMID 27293546, 2016). "The characteristics of these mice are: lipodystrophy, organomegaly, decreased leptin and adiponectin in plasma, insulin resistance, elevated free fatty acids (FFAs) and hypotension." (PMID 27483259, 2016). "Recently, metreleptin, a recombinant analogue of human leptin, has been approved for the treatment of metabolic derangements of lipodystrophy." (PMID 26987365, 2016). "Leptin has, therefore, been approved in Japan and USA for the treatment of diabetes and hypertriglyceridemia in patients with lipodystrophy." (PMID 27649157, 2016). "Leptin levels are altered in lipodystrophy, and leptin therapy has been applied to improve insulin sensitivity in HIV-associated lipoatrophy, but with diverging results." (PMID 26244048, 2015). "Leptin levels were significantly elevated in lipodystrophy of the Hypertrophic or Mixed type (Hyper/Mix) compared to HIV-infected patients without lipodystrophy (Non-Lipo)." (PMID 26244048, 2015). "The levels of leptin were higher in patients with isolated central fat accumulation and mixed forms of lipodystrophy and lower in those with isolated lipoatrophy." (PMID 24958357, 2014). "Leptin levels were lower in patients with lipodystrophy, indicating its close relationship with total body fat." (PMID 24958357, 2014). "In our sample, HIV-infected patients with isolated central fat accumulation and mixed forms of lipodystrophy had higher BMI and leptin levels." (PMID 24958357, 2014). "For example, leptin deficiency is associated with hypertriglyceridemia, low HDL C, and low insulin sensitivity in cases of acquired or congenital lipodystrophies; leptin therapy reverses the metabolic dysfunction." (PMID 23533722, 2013). "The present study explored the effect of leptin infusion on the pathogenesis of diet-induced lipodystrophy in mice." (PMID 18348717, 2008). "The present study explores the effect of leptin infusion on the pathogenesis of diet-induced lipodystrophy in mice." (PMID 18348717, 2008). "In the present study, we investigated the effects of leptin infusion on insulin sensitivity and lipid metabolism in diet-induced lipodystrophy model mice." (PMID 18348717, 2008). "All mice were fed normal or lipodystrophy model diets for 4 weeks and were infused intrapeneally 0 or 5 μg of leptin per day from third week of the feeding period for 1 week." (PMID 18348717, 2008).
lipodystrophy (continued). "Lower serum leptin levels and off-target effects of certain drugs on the leptin pathway have been suggested, which could alter energy homeostasis and food intake leading to lipodystrophy." (PMID 39307897, 2025). "Moreover, clinical studies have identified beneficial effects of metreleptin on cognitive function in individuals with low leptin levels due to lipodystrophy." (PMID 41462981, 2025). "Our findings, in conjunction with existing literature, suggest that monitoring IGF-1 levels may offer additional insights into the effectiveness of leptin replacement therapy in managing lipodystrophy and related metabolic complications." (PMID 40520449, 2025). "Indeed, metreleptin, which is a modified synthetic form of human leptin, has already been approved for treatment of lipodystrophy." (PMID 41462981, 2025). "Leptin levels were positively correlated with AOM distance in lipodystrophy (r = .513, P < .001)." (PMID 39352627, 2025). "Impaired leptin signaling in lipodystrophy may affect the secretion of gonadotropins and gonadal steroids, which may influence puberty development and fertility." (PMID 38183080, 2024). "In a recent non-randomized crossover study of 25 patients with lipodystrophy who were leptin-deficient, metreleptin was associated with increasing the resting metabolic rate and, improved the metabolic parameters." (PMID 38715796, 2024). "Therefore, several clinical trials tested the effectiveness of exogenous leptin administration to patients suffering from lipodystrophy." (PMID 37239098, 2023). "Due to the emergence of leptin replacement therapy, which has primarily been utilized for the treatment of lipodystrophy, future studies targeting this adipokine pathway in individuals with reduced muscle loss may be an important area of research." (PMID 37737171, 2023). "Furthermore, patients with lipodystrophy, especially GL, are typically hyperphagic due to the reduced levels of the adipokine, leptin, which is a key physiological regulator of satiety, energy homeostasis, insulin action and lipid metabolism." (PMID 37237416, 2023). "Leptin replacement in patients with lipodystrophy reduces serum TGs." (PMID 36689070, 2023). "Leptin replacement with metrelepin in patients with lipodystrophy results in increased satiety." (PMID 35904713, 2022). "Leptin efficacy shown in mice was then confirmed also in human patients with lipodystrophy." (PMID 35600578, 2022). "Human recombinant leptin (metrelin) is the only organokine that has been approved in the treatment of non-HIV associated lipodystrophy." (PMID 35355551, 2022). "Likewise, leptin therapy in patients with hypothalamic amenorrhea and lipodystrophy leads to increases in IGF1 concentrations." (PMID 34002033, 2021). "Therefore, administration of human recombinant leptin improves many metabolic defects in patients with lipodystrophy." (PMID 33935782, 2021). "In addition, Hp infection can also inhibit the release of leptin from white adipose tissue, which can decrease de novo lipogenesis in patients with lipodystrophy and eventually reduce very low-density lipoproteins (VLDL) production." (PMID 34918746, 2021). "Though not assessed here, leptin plays a key role in the regulation of bone mass and its deficiency has been proposed to be causal in driving the bone phenotype in lipodystrophy." (PMID 35145475, 2021). "Nevertheless, further studies are necessary to investigate the effects of lipodystrophy and leptin on resistance arteries function, and determine whether higher doses of leptin can reduce blood pressure in patients with lipodystrophy." (PMID 34638939, 2021). "Leptin administration is also widely used in patients with lipodystrophy." (PMID 33935782, 2021). "Bone formation also increased in mice with severe lipodystrophy induced by a knock-out of peroxisome proliferator-activated receptor gamma (PPARγ) in white fat and the inverse correlation between bone density and MAT was also observed in leptin-deficient mice." (PMID 34574647, 2021).
lipodystrophy (continued). "Furthermore, leptin replacement therapy (metreleptin) in patients with lipodystrophy decreased significantly serum ANGPTL3 levels, total cholesterol and triglyceride concentrations." (PMID 33273510, 2020). "Leptin and adiponectin, typical adipokines, play important roles in lipodystrophy." (PMID 32821266, 2020). "A role of leptin in hepatic lipid handling is highlighted by the observation that recombinant leptin reverses steatosis of hypoleptinemic patients with lipodystrophy by an unknown mechanism." (PMID 31222048, 2019). "These rodent data are partially recapitulated in individuals with lipodystrophy which exhibit chronically low levels of leptin and are at a greater risk to the development of OSA, suggesting that insufficient leptin action may lead to OSA in humans." (PMID 30127766, 2018). "Recently, leptin administration received approval for the treatment of lipodystrophy, making it more likely that leptin administration in patients with AN could follow in the near future." (PMID 29099750, 2017). "However, serum leptin level in our patient was less than 10 μg/L, which is 69 % sensitive and 78 % specific for lipodystrophy." (PMID 26976018, 2016). "However, the effects of leptin are less significant in patients with partial lipodystrophies and other laminopathies, than in those with generalised lipodystrophies." (PMID 25885670, 2015). "The leptin therapy gives good results in diabetic and nondiabetic patients with lipodystrophy, who have significantly reduced production of endogenous leptin due to a deficiency of fat mass." (PMID 28031898, 2015). "Likewise, subjects with lipodystrophy who lack leptin have also been successfully treated with leptin replacement therapy." (PMID 24701352, 2014). "Low leptin levels can also be the result of rare genetic disorders such as lipodystrophies." (PMID 24822223, 2014). "Therefore, there are no standardized cut-offs for leptin and adiponectin levels to confirm or exclude the diagnosis of lipodystrophy, and they are not currently recommended as diagnostic tools." (PMID 40892266, 2025). "Lipoatrophy, low serum leptin and adiponectin levels, as well as adipose tissue mitochondrial defects, oxidative stress and increased expression of some thermogenic markers, provide evidence of adipose tissue dysfunction in patients with MFN2-associated lipodystrophy." (PMID 35046902, 2021). "Notably, patients with lipodystrophy display low circulating levels of leptin (hypoleptinemia)." (PMID 33935782, 2021). "Interestingly, while leptin displays anti-steatotic properties as shown by the benefices of leptin treatment in lipodystrophy, which will be commented on through this manuscript, high plasma levels are associated with inflammatory and fibrogenic processes and possibly oncogenic effects on the liver." (PMID 33316927, 2020). "Recent studies have suggested that lean Type two diabetics have an oligogenic form of lipodystrophy and these data further suggest that relatively decreased leptin levels in this cohort may be an important component of their phenotype, a possibility that has not been formally tested." (PMID 32452759, 2020). "Thus, even though this was a small clinical trial these results are in line with previous human studies indicating that regardless to the disease context (e.g. lipodystrophy, hypothalamic amenorrhea) leptin therapy is efficacious only in severely hypoleptinemic subjects." (PMID 31391467, 2019). "We presented several mouse models of lipodystrophy which reproduce well the metabolic and cardiovascular phenotype of patients with lipodystrophy and represent the perfect avenue to investigate the direct effects of leptin on the cardiovascular system and dissipate any potential harmful effect." (PMID 31656583, 2019). "Leptin levels were positively correlated with TF-SMA and TF-RR distances in patients with lipodystrophy (r = .717, P < .001 and r = .721, P < .001, respectively)." (PMID 39352627, 2025).
lipodystrophy (continued). "Leptin analogs, particularly metreleptin, are effective for patients who cannot produce leptin naturally and are the only FDA-approved replacement therapy for certain lipodystrophy cases." (PMID 40154074, 2025). "Leptin replacement may decrease ApoC-III by reducing plasma fasting glucose levels, as it has been demonstrated in leptin deficient ob/ob mice, but in humans, it is not enough to manage the metabolic complications of lipodystrophy, in particular hypertriglyceridemia." (PMID 36689070, 2023). "To investigate the molecular pathogenesis of MFN2 R707W-related lipodystrophy, and the role of MFN2 in leptin synthesis and secretion, we generated and characterised homozygous Mfn2R707W/R707W mice." (PMID 36722855, 2023). "Another study in patients with lipodystrophy reported that A-FABP serum concentration correlated with gender and serum leptin as well as BMI22." (PMID 32753620, 2020). "Low leptin and adiponectin levels are more common in persons with HIV and correlate with lipodystrophy." (PMID 25915208, 2015). "Our aim was to evaluate adipocyte-derived hormones (adiponectin, leptin, resistin, TNF-α, PAI-1) and ghrelin plasma levels and their relationship with IR in HIV-infected patients according to the presence of lipodystrophy and fat redistribution." (PMID 24958357, 2014). "In conclusion, leptin levels appear to be primarily determined by total adiposity in HIV-infected individuals, independently of the presence of lipodystrophy." (PMID 24958357, 2014). "Previous studies demonstrated that leptin treatment attenuated insulin resistance in genetically diabetic mice (such as ob/ob mice and MKR mice) and in lipodystrophy model transgenic mice (such as aP2-SREBP-1c mice)." (PMID 18348717, 2008). "No reliable serum leptin cutoff point has been identified for selecting lipodystrophy patients who respond to metreleptin." (PMID 40452043, 2025). "Metreleptin, a leptin analogue, is approved in various countries for leptin deficiency in non-HIV-related lipodystrophy and has been shown to improve metabolic complications in AGL." (PMID 41476924, 2025). "Given the potent therapeutic effects of leptin replacement on glucose homeostasis and liver steatosis in lipodystrophic mice and humans, we speculated whether elevated leptin levels might explain the apparent absence of lipodystrophy-associated metabolic dysfunction in iAKO mice." (PMID 38811804, 2024). "As a result, lipodystrophy-induced decrease of plasma leptin but not adiponectin levels in Seipin/Apoe dKO mice was partially reversed by AT." (PMID 38525541, 2024). "Adipose tissue of ADGAT DKO mice maintained the ability to synthesize and secrete adipose-derived hormones, such as leptin, which is crucially absent in typical lipodystrophy." (PMID 37782317, 2023). "Lipodystrophies are a heterogeneous group of rare disorders characterized by lack or dysfunction of white adipose tissue (WAT) with perturbation in its mass or distribution and consequent alterations in adipokines levels, mainly leptin and adiponectin." (PMID 37501786, 2023). "Lipodystrophy (LD) syndromes are rare heterogeneous disorders characterized by reduction or absence of subcutaneous fat, low or nondetectable leptin concentrations in blood and impaired hunger/satiety regulation." (PMID 36037795, 2022). "Since AT transplantation and leptin replacement improve the renal function, the kidney phenotype is likely a consequence of the lipodystrophy and not a cell autonomous function of seipin." (PMID 35250856, 2022). "Together, these results indicate that 8wk of HU induces significant lipodystrophy in mice, and as such serum leptin levels do not correlate with MAT accumulation as observed in diet-induced obese mice." (PMID 34836964, 2021). "When leptin is administered to these animals, the metabolic disorders are corrected and also the liver fat content is reduced, but lipodystrophy is not corrected." (PMID 33233602, 2020).